EZH2 (enhancer of zeste 2 polycomb repressive complex 2 subunit)
Diseases named in the same sentence as EZH2 in open-access papers (continued):
Sharing a sentence is not in itself a finding about the gene and the disease.
multiple myeloma (87 papers, 2011 to 2025). "High expression of EZH2 is associated with poor outcome in hematologic malignancies (myeloma and chronic lymphocytic leukaemia)." (PMID 38804044, 2024). "For example, acute myeloid leukemia and multiple myeloma cell lines with KDM6A mutations are more sensitive to EZH2 inhibitors than KDM6A wild-type expressing lines." (PMID 35137163, 2022). "A high RNA risk score value is associated with a higher EZH2 inhibitor efficacy in patient myeloma cells." (PMID 34683129, 2021). "Since EZH2 is overexpressed in myeloma cells in association with a poor outcome, it would be interesting to explore the potential role of alternative EZH2 splicing regulated by SF3B3 in plasma cell tumorigenesis and disease progression." (PMID 34683129, 2021). "The Yang laboratory found that mature adipocytes in bone marrow protect myeloma cells against chemotherapy through autophagy activation and that myeloma-associated adipocytes contribute to bone disease through PPARγ, EZH2, and PRC2-related mechanisms." (PMID 33498240, 2021). "Given the evidence associating EZH2 expression and oncogenesis in other cancers, we investigated its effect in myeloma patients." (PMID 28362441, 2017). "In this study, 17-AAG, an HSP90 inhibitor candidate in human clinical trials (multiple myeloma; phase 3), potentially exerted an inhibitory activity on EZH2, PAX5 and KHDRBS1 genes associated with the risk of developing metastatic phenotypes by modulating gene expression." (PMID 38254687, 2024). "Following the initial observation that EZH2 is over expressed in aggressive myelomas, we demonstrated that EZH2 expression is driven by IL-6 and is required for the proliferation of growth-factor-independent human myeloma cell lines (HMCLs) harboring a ras mutation." (PMID 29774113, 2018). "Our study demonstrates that EZH2 inhibition may be an effective therapeutic strategy for myeloma patients, potentially even for those with high-risk disease for whom current approaches are ineffective." (PMID 28362441, 2017). "For the first time, we have identified an association between EZH2 expression and survival in myeloma that is robust across different data sets, persists regardless of therapy used and is independent of other factors known to influence myeloma patient survival." (PMID 28362441, 2017). "Thus, the focal increase of H3K27 methylation in the presence of MMSET may have a similar effect as UTX mutations, suggesting that EZH2 plays an important, and so far underappreciated, role in multiple myeloma." (PMID 25188243, 2014). "Here, we identified a myeloma-associated lncRNA, PLUM, that mediates chemoresistance through interacting with EZH2." (PMID 40890111, 2025). "Within the bone marrow microenvironment, adipocyte-derived IL-6 and TNFα enhance EZH2 expression in myeloma cells." (PMID 40756901, 2025). "According to Rastgoo, the connection between RBPMS and miR-138 played a role in the drug sensitivity of multiple myeloma (MM) with the influence of the enhancer of zeste homolog (EZH2)." (PMID 38305808, 2024). "Epigenetic modifications play an important role in cellular senescence, and enhancer of zeste homolog 2 (EZH2) is a key methyltransferase involved in epigenetic remodeling in multiple myeloma (MM) cells." (PMID 38804044, 2024). "Dual inhibition of G9a (H3K9 methyltransferase) and EZH2 (a H3K27methyltransferase) exerts a strong antitumor effect in myeloma." (PMID 35409271, 2022). "There are extensive data demonstrating the essential role of EZH2 in the incidence of multiple human malignancies such as multiple myeloma, lymphoma, melanoma, thyroid, prostate, breast, bladder, and liver cancers." (PMID 35668081, 2022). "Recent studies indicate that dual inhibition of DNMTs and EZH2 exhibits synergistic antineoplastic activity against human myeloid leukemia cells, and can resensitize the resistant myeloma cells to both lenalidomide and pomalidomide in vitro." (PMID 34175897, 2021).
multiple myeloma (continued). "Accordingly, rebalancing of H3K27me3 levels at specific genes through EZH2 inhibitors has been proposed as a therapeutic strategy in cases of multiple myeloma and urothelial bladder carcinomas harboring KDM6A/UTX mutations." (PMID 34153035, 2021). "This study aims to reveal thepositive effect of miR-124 on CDKN2A gene expressionthrough targeting EZH2 gene and also evaluate phenotypicchanges in myeloma cell line." (PMID 31606963, 2020). "In hematological malignancies (leukemia, lymphomas, and myelomas) mutations in epigenetic modifiers such as JAK2, DNMT3A, IDH2, or EZH2 are common hallmarks of these diseases." (PMID 32492865, 2020). "Analysis of gene expression profiles of pretreatment samples from multiple myeloma patients enrolled on the APEX039 clinical study revealed that high levels of EZH2 expression is indicative of poor response to bortezomib treatment." (PMID 30761216, 2018). "Further investigation is demanded, however, to fully understand the role of EZH2 in myeloma resistance to IMiDs." (PMID 30761216, 2018). "Global gene expression profiling indicated that, while EZH2 is upregulated, its target genes are downregulated in myeloma cells compared with normal plasma cells." (PMID 30285865, 2018). "Our data suggest that simultaneous inhibition of DNA methyl transferases and EZH2 leads to an extensive epigenetic reprogramming which allows myeloma cells to (re)gain sensitivity to IMiDs." (PMID 29130642, 2018). "EZH2 can function as an oncogene in multiple myeloma (MM) by repressing tumor suppressor genes that control apoptosis, cell cycle control and adhesion properties." (PMID 30761216, 2018). "More recently, EZH2 inhibition as single treatment demonstrated anti-myeloma activity only in a subset of HMCLs despite the global decrease in H3K27me3 levels." (PMID 30761216, 2018). "To evaluate the single agent efficacy of EZH2 inhibition as an anti-MM therapeutic strategy we treated a panel of 14 human myeloma cell lines (HMCLs) with the selective EZH2 inhibitors (EZH2i’s) EPZ-6438 and GSK-126." (PMID 29774113, 2018). "Using this approach, we demonstrate the in vitro efficacy of EZH2 inhibition in both myeloma cell lines and in primary patient samples despite the protective effect of a modelled BM niche." (PMID 28362441, 2017). "Using two chemically distinct small-molecule inhibitors, we demonstrate a reduction in myeloma cell proliferation with EZH2 inhibition, which leads to cell cycle arrest followed by apoptosis." (PMID 28362441, 2017). "Here we further investigated the anti-myeloma effects mediated by pharmacological inhibition of EZH2 by focusing on downregulated genes in MM and the molecular mechanisms underlying this observation." (PMID 28052011, 2017). "Here we further dissect the anti-myeloma mechanisms mediated by EZH2 inhibition and show that pharmacological inhibition of EZH2 reduces the expression of MM-associated oncogenes; IRF-4, XBP-1, PRDM1/BLIMP-1 and c-MYC." (PMID 28052011, 2017). "We have previously presented the histone methyltransferase enhancer of zeste homolog 2 (EZH2) of the polycomb repressive complex 2 (PRC2) as a potential therapeutic target in Multiple Myeloma (MM)." (PMID 28664185, 2017). "Using two chemically distinct, specific, small-molecule inhibitors in myeloma cell lines and primary patient cells, we demonstrate EZH2 to be a therapeutic target in myeloma, including cases with high-risk features." (PMID 28362441, 2017). "Although the use of EZH2 inhibitors in the context of NSD mutations has not been studied, one recent report suggested a promising mechanism for application of EZH2 inhibitors in NSD2-overexpressing myeloma cells." (PMID 29176703, 2017). "EZH2 is a critical epigenetic regulator that is deregulated in various types of cancers including multiple myeloma (MM)." (PMID 27926488, 2017).
multiple myeloma (continued). "In summary, we present evidence that EZH2 is an important therapeutic target in myeloma and suggest that clinical trials of EZH2 inhibitors enrolling myeloma patients should be considered." (PMID 28362441, 2017). "Drugs targeting epigenetic modifiers (e.g., HDACs, EZH2) can sensitize MM-resistant cells to anti-myeloma drugs and reversibility of epigenetic changes makes these drugs promising therapeutic agents." (PMID 28623912, 2017). "For the first time, we have identified and validated a robust and independent deleterious effect of high EZH2 expression on outcomes in myeloma patients." (PMID 28362441, 2017). "In order to identify a potential biomarker of response, we next looked across our original panel of eight myeloma cell lines incubating cells over 6 days, a time point at which we had seen the most variability in response to EZH2 inhibition." (PMID 28362441, 2017). "We also demonstrated that pharmacological inhibition of EZH2 had anti-myeloma effects in both MM cell lines and CD138+ MM patient cells." (PMID 26755663, 2016). "Considering this, and the fact that UNC1999, as well as other novel EZH2 inhibitors, are available for use in vivo, it remains to be evaluated if EZH2 will constitute a novel druggable target with potent anti-myeloma effect in relevant murine models of MM." (PMID 26755663, 2016). "Together, our work elucidates previously unrecognized interplay between MMSET and EZH2 in myeloma oncogenesis and identifies domains to be considered when designing inhibitors of MMSET function." (PMID 25188243, 2014). "Together, we conclude that MMSET overexpression alters the genomic organization of EZH2 across the myeloma genome and this effect, similar to other cancers, induces misregulation of specific Polycomb target genes that contribute to pathogenesis." (PMID 25188243, 2014). "We propose that overexpression of MMSET in myeloma plays a role in establishing chromatin boundaries leading to accumulation of EZH2/H3K27me3 and gene repression on one side of the insulator." (PMID 25188243, 2014). "As EZH2 has recently been implicated in a number of haematological malignancies, we examined the potential functional relevance of increased EZH2 expression in CD138− myeloma cells." (PMID 23985559, 2013). "Recently, methyltransferase inhibitor DZNep has been reported to decrease PRC2 proteins, including EZH2, and trigger caspase mediated apoptosis in myeloma cells." (PMID 23985559, 2013). "It is thus plausible that interaction between EPC1 and EZH2 within myeloma SP cells contributes to their proliferation as well as to cancer stem cell maintenance." (PMID 23469177, 2013). "Furthermore, dual G9a and EZH2 inhibition reduces myeloma cell proliferation by modulating the interferon signal and the IRF4-MYC axis." (PMID 35409271, 2022). "High expression of EZH2 relates to the poor prognosis of multiple myeloma." (PMID 35668081, 2022). "Also, EZH2 inhibition resulted in the subsequent reduction in myeloma cell proliferation and an increase in cell cycle entry." (PMID 35668081, 2022). "EZH2 inhibition induces anti-myeloma impacts on multiple myeloma." (PMID 33685449, 2021). "Our recent findings defining a distinct metabolic signature upon response to enhancer of zeste homolog 2 (EZH2) inhibition in multiple myeloma (MM) highlight how a shift of preferred metabolic pathways may potentiate novel treatments." (PMID 34968247, 2021). "In addition, the deregulation of the repression loop between EZH2 and miR-138 also participates in the resistance of myeloma cells to bortezomib by a mechanism that involves the tumor suppressor gene RBPMS." (PMID 33126754, 2020). "Inhibitors targeting both EZH1 and EZH2 (EZH1/2 dual inhibitors) and EED (EED inhibitor) have also been developed, and these inhibitors show better tumor-eradicating effects than EZH2-specific inhibitors in the treatment of AML, multiple myeloma, and EZH2 inhibitor-resistant DLBCL cells." (PMID 33374737, 2020).
multiple myeloma (continued). "In multiple myeloma (MM), downregulated miR-138 brings about the upregulation of EZH2 target gene." (PMID 31752930, 2019). "Whether IMiD-resistant myeloma cells utilize EZH2 to manipulate the TGF-β functions by regulating SMAD3 expression to gain proliferative advantage over the antitumor effects is an important concept." (PMID 30761216, 2018). "In conclusion, our data suggests that while only a subset of human myeloma cell lines respond to EZH2 inhibition, nearly all lines tested were effectively targeted for cell death through a synergistic combination of panobinostat and EZH2 inhibitor pre-treatment." (PMID 29774113, 2018). "Herein we summarize the current knowledge on the role of EZH2 in multiple myeloma (MM)." (PMID 30761216, 2018). "Studies have highlighted the various roles of EZH2 in the pathophysiology of multiple myeloma (MM)." (PMID 30555699, 2018). "We and others have investigated the anti-myeloma activity of EZH2 inhibitors." (PMID 30761216, 2018). "We investigated whether EZH2 inhibition could enhance the anti-myeloma activity of melphalan, bortezomib, and lenalidomide treatment." (PMID 30285865, 2018). "Therefore, we review the current knowledge on the regulation of EZH2 and its biological impact in MM, the anti-myeloma activity of EZH2 inhibitors and their potential as a targeted therapy in MM." (PMID 30761216, 2018). "This reinforces the importance of EZH2 expression in myeloma pathogenesis." (PMID 28362441, 2017). "Importantly, we demonstrate that PTC-209 exhibits synergistic and additive anti-myeloma activity when combined with other epigenetic inhibitors targeting EZH2 and BET bromodomains." (PMID 29262596, 2017). "We therefore sought to investigate the effect of EZH2 inhibition in myeloma in vitro." (PMID 28362441, 2017). "Using large data sets totalling almost 1500 patients in several phase III clinical trials using different therapeutic strategies, we, for the first time, identify and validate a robust and independent deleterious effect of high EZH2 gene expression on outcomes in myeloma patients." (PMID 28362441, 2017). "In addition, we and others have recently demonstrated that targeted inhibition of the PRC2 enzymatic subunit EZH2 by highly selective inhibitors had anti-myeloma effects." (PMID 29262596, 2017). "We find that inhibition of EZH2 in myeloma induces cell cycle arrest followed by apoptosis." (PMID 28362441, 2017). "Our results suggest that EZH2 inhibition may be a potential therapeutic strategy for the treatment of myeloma and should be investigated in clinical studies." (PMID 28362441, 2017). "In the present study, we hypothesized that targeting EZH2 might induce apoptosis in myeloma cells including stem cell-like cells (CSCs)." (PMID 27926488, 2017). "In this study, the aim was to investigate the genome-wide distribution of H3K27me3 and H3K4me3 in MM and to test whether pharmacological inhibition of the methyltransferase activity of EZH2 would demonstrate anti-myeloma potential." (PMID 26755663, 2016). "While germinal cell lymphoma is associated with gain-of-function mutations of EZH2, multiple myeloma has not been linked directly to alterations in EZH2 function." (PMID 25188243, 2014). "This suggests bortezomib reduces myeloma SP cell clonogenicity by acting on both Aurora B and EZH2." (PMID 23469177, 2013). "Hence, our data on characterization of the myeloma-associated expression of PLUM and its role in enhancing EZH2 stability and activity towards chemoresistance suggest its promising potential and future development as a biomarker and/or therapeutic target for MM." (PMID 40890111, 2025). "Moreover, it was found that miR-124 could exert a tumor inhibitory effect on multiple myeloma cell line by targeting EZH2." (PMID 34857740, 2021).
multiple myeloma (continued). "Collectively, these data may suggest EZH2 as mediator of resistance to proteasome inhibition in multiple myeloma and highlight that the combination of EZH2 and proteasome inhibitors might be useful in both newly diagnosed as well as proteasome inhibitor refractory MM patients." (PMID 30761216, 2018). "In addition to their anti-myeloma activity as single agents, EZH2 inhibitors may be effective anti-myeloma agents in combination with clinically relevant myeloma regimens." (PMID 30761216, 2018). "Thus, our study suggests that the specific local changes may outweigh the gross global changes we frequently observe in cancer and implicates EZH2 as a novel therapeutic target in myeloma cells." (PMID 25188243, 2014). "For instance, a clear role has been established for the histone methyltransferases (HMTs) multiple myeloma SET domain (MMSET) and enhancer of zeste 2 (EZH2) in the DR against the alkylating agent melphalan and PIs/IMiDs respectively." (PMID 40241199, 2025). "Physical and functional interactions between NSD2 and other chromatin regulators, such as EZH2 and SMARCA2, further reprogram the chromatin landscape, promoting myeloma growth, altering enhancer activity, and sustaining drug resistance." (PMID 40563566, 2025). "Collectively, our data indicate PLUM recruits PRC2 core complex factors by binding to EZH2 and suggest that this RNP complex is critical for enhancing PRC2-mediated histone trimethylation to promote myeloma functions." (PMID 40890111, 2025). "Some approaches can upregulate the target antigen expression to enhance CAR-T efficacy, as reported for upregulation of BCMA by a γ-secretase inhibitor in myeloma, and GD2 upregulation upon EZH2 inhibition in Ewing Sarcoma." (PMID 37964302, 2023). "Studies show that inhibition of EZH2/G9a upregulates interferon (IFN)-stimulated genes and suppresses IRF4-MYC axis genes in multiple myeloma." (PMID 35409271, 2022). "In MM cell lines, pharmacological inhibition of EZH2 decreased the global H3K27 methylation and had anti-myeloma effects both in vitro and in vivo." (PMID 34857028, 2021). "In multiple myeloma, MALAT1 positively regulates NRF1 and NRF2 through the transcriptional inhibition of Keap1 by EZH2, which is a component of the PRC that induces H3K27me3 through a mechanism still under study." (PMID 32492865, 2020). "Bortezomib has been reported to indirectly reduce EZH2 transcription and decrease E2F1 activity in myeloma cells." (PMID 33126754, 2020). "For instance, EZH2 inhibition by GSK343 and UNC1999 demonstrates anti-myeloma activity by reducing the survival of MM cell lines and CD138+ MM cells isolated from newly diagnosed patients." (PMID 30761216, 2018). "In support of this notion, the combination of EZH2 and BMI-1 (PRC1) inhibitors have synergistic anti-myeloma activity using HMCLs and CD138+ myeloma cells isolated from newly diagnosed or relapsed MM patients." (PMID 30761216, 2018). "Using Affymetrix microarrays, we analyzed the expression of PRC2 core genes EZH2, SUZ12, and EED in normal bone marrow plasma cells (BMPCs, n = 5), primary myeloma cells from patients (MMCs, n = 206), and human myeloma cell lines (HMCLs, n = 26)." (PMID 30285865, 2018). "EZH2 is also activated in many cancers, UTX, an H3K27me3 demethylase, is inactivated in multiple myeloma, esophageal, renal and bladder and in other cancers, the demethylase JMJD3 is expressed at very low levels therefore leads high level of H3K27me3." (PMID 27845897, 2017). "In both data sets, the impact of EZH2 expression remained significant on multivariate analysis, demonstrating its effect is independent of other factors known to affect survival in myeloma patients including International Staging System, GEP70 risk and adverse cytogenetics." (PMID 28362441, 2017). "Global gene expression profiling indicated that EZH2 is up-regulated in monoclonal gammopathy of undetermined significance (MGUS) and aggressive myeloma cells compared with normal plasma cells." (PMID 26497210, 2016).